CD4 (CD4 molecule)
Diseases named in the same sentence as CD4 in open-access papers (continued):
Sharing a sentence is not in itself a finding about the gene and the disease.
tumor (continued). "Meanwhile, CD4 TILs were identified as significant predictors when evaluated in tumor stroma rather than tumor cell nests." (PMID 36662367, 2023). "The activity of immune cells in the high GNG4 expression group decreased, including activated CD4+ T cells and CD8+ T cells, macrophages, Th1 cells, NK cells, DCsl and Th17 cells, leading to reduced TME infiltration, which promoted the growth of the tumour." (PMID 37448185, 2023). "Notably, HLA-G was correlated with the levels of TILs, including CD4+ T cells, CD8+ T cells and MDSCs, which suggested that HLA-G plays an important role in the tumor environment." (PMID 37875821, 2023). "However, CD4+ and CD8+ CD69+CD103+ sTRM cells expanded with FTY720 treatment compared with 0 day group before the tumor rechallenge." (PMID 37407600, 2023). "In addition, in glioblastoma, high expression of ICOSLG promotes the proliferation of CD4+ T cells by stimulating the secretion of IL-10, but knocking out ICOSLG of tumor cells increases the number of CD8+ T cells." (PMID 37842091, 2023). "Moreover, analyses of the CBPA-treated mice further showed remarkably increased levels of tumor-infiltrating CD4+ and CD8+ T cells and cytokine secretion in the tumor microenvironment." (PMID 36835382, 2023). "The tumor control group and paclitaxel group had similar CD3+, CD4/CD8, and CD8+ levels." (PMID 36902470, 2023). "For iCCA, it is described that the CD4 T regulatory cells (Tregs) create a highly immunosuppressive environment, influencing the anti-tumor response in a negative way." (PMID 36980192, 2023). "The results from xCell and CIBERSORT consistently indicated that killer cells such as memory CD4 T cells and central memory CD8 T cells, which play critical roles in anti-tumor immunity and immunotherapy, were significantly richer in the PI3K pathway mutation group." (PMID 36864522, 2023). "Further immune-cell-subtype analysis conducted by single-cell RNA sequencing showed that tumor cell pyroptosis significantly boosted the populations of CD4+, CD8+, NK, and M1 macrophage cells in tumor immune microenvironment, thus leading to a powerful immunogenic response in cancer." (PMID 36823153, 2023). "This protection was antigen-specific, as mice receiving 3 × 106 activated polyclonal CD4+ T cells not expressing the CLTCH129>Q-specific TCR had tumor growth comparable to untreated mice." (PMID 37400675, 2023). "CD4+ T cells and CD4+ chimeric antigen receptor (CAR) T cells display highly variable antitumor activity in preclinical models and in patients; however, the mechanisms dictating how and when CD4+ T cells promote tumor regression are incompletely understood." (PMID 37248395, 2023). "CD4+ and CD8+ effector T cells play a key role in the anti-tumor process via different mechanisms." (PMID 37188191, 2023). "In addition, DHA combined with anti-PD-1 treatment promoted CD4+ T cell infiltration in spleen and CD8+ T cell infiltration in tumor tissue." (PMID 38155974, 2023). "Virotherapy promotes the infiltration of CD4+ and CD8+ T cells into the tumor tissue." (PMID 36618103, 2023). "CD4+ and CD8+ T cells are primarily responsible for tumor growth and cancer progression." (PMID 36983053, 2023). "Therefore, OIX_NPs increased the effective intratumoral infiltration of CD4 and CD8 T cells, which induced tumor cells apoptosis, necrosis, and autophagy, thereby inhibiting tumor growth." (PMID 36437106, 2023). "After different treatments, there were no significant changes in the F4/80+ area or CD4+ cell count in both tumor models." (PMID 37304301, 2023). "Immunofluorescence staining showed that more CD4+ and CD8+ T cells were found in tumor tissues with T cell adoption than in the PBS groups, while the frequencies of CD4+ and CD8+ T cells in the CAR T and TIL CAR-T cell groups were statistically higher than those of their corresponding mock T groups." (PMID 38067271, 2023).
tumor (continued). "SLC35A2 may further affect tumor immunity mainly by regulating CD8+T cells, NK cells, B cells, and CD4+T cells, and the effect of SLC35A2 on immunity varies across tumor types." (PMID 37275857, 2023). "Average tumor volume growth after treatment indicated mice vaccinated with PancVAX2 experienced a significant decrease in average tumor volume compared with mice treated with PBS, CD4 vaccine, or CD8 vaccine." (PMID 38063199, 2023). "Similarly, the proportion of CD4+ T helper 1 (TH1) effectors increased relative to regulatory CD4+ TREG cells in intermediate (D14) and late stage (D21) tumours (decreasing CD4+FoxP3+/CD4+T-bet+ ratio)." (PMID 37153625, 2023). "The increase in the population of memory CD4+ T cells (39.4%) and memory CD8+ T cells (44.7%) in the spleen tissues of the mice after 28 days suggested antitumoral immunological memory that prevented tumor metastasis and recurrence." (PMID 36987269, 2023). "However, by treating mice with anti‐CD8 or anti‐CD4 antibodies, FMRP‐KO showed significant reduction of CD8 T cells in the blood, strong tumor growth, short survival and the worse therapeutic effect of anti‐PD‐1." (PMID 36968189, 2023). "In detail, combination therapy was able to induce a strong antitumor immune response, characterized by increased tumor infiltration of CD4+ and CD8+ T-cells and a reduced frequency of MDSCs, resulting in increased tumor regression and prolonged survival in metastatic mice." (PMID 37047419, 2023). "Cytotoxic CD4+ T cells have also been shown to contribute to durable immune checkpoint blockade responses in NSCLC patients by directly killing HLA-II-expressing tumor cells and augmenting HLA-I-dependent cytotoxic CD8+ T cell anti-tumor responses." (PMID 38062068, 2023). "In addition, ICOSLG was positively correlated with Foxp3+ cells and negatively correlated with CD4+ T cells, indicating that ICOSLG is closely related to the immunosuppressive process in the tumor microenvironment." (PMID 37842091, 2023). "Besides, B cells can act as antigen-presenting cells (APCs) to present specific antigens to CD4 and CD8 T cells, and thereby maintain and expand long-term antitumor immunity within the tumor microenvironment." (PMID 37950236, 2023). "To activate the adaptive immune response to tumors, we detected the expression of CD11c, MHC II, CD86, CD4, CD8, and CD69 in mouse transplanted tumors by IHC and studied the infiltration and activation of DCs and CD4+ T, and CD8+ T cells in the tumor microenvironment after (−)-Guaiol intervention." (PMID 36441354, 2023). "Furthermore, a considerable increase in tumor-infiltrating CD8+ and CD4+ T cells, as well as macrophages and NKs, was found in tumors treated with ox-MWCNTs–hypothermia combination therapy." (PMID 37047572, 2023). "Expression of PD‐1 on both CD8+ and CD4+ T cells isolated from tumour tissue but not surrounding normal bladder tissue was significantly higher than on T cells isolated from the peripheral blood." (PMID 37025470, 2023). "The binding of BCRs and tumor antigens not only increases the secretion of cytokines that induce the activation of CD4+ T cells, CD8+ T cells, and NK cells, but also directly kills tumor cells through the secretion of cytolytic molecules, such as GZMB and TRAIL." (PMID 38203530, 2023). "Since T cells kill not only virus-free tumor cells but also virus-infected tumor cells, the infected tumor cells are lysed via anti-tumor adaptive immune cells CD8+ T cells (directly killing) with δxXmx+XTi and by CD4+ T cells (indirectly killing through cytokines) with δcTimt+TiC." (PMID 36766849, 2023). "Quantification of MYC intensities in tumor cells and densities of immune cell types in consecutive slides revealed a significant negative correlation between MYC expression and infiltration of CD3+, CD4+, FOXP3+, pSTAT1+, and MHCII+ immune cells." (PMID 37642941, 2023).
tumor (continued). "Moreover, ITI-3000 induced a favorable tumor microenvironment (TME), including Th1-type cytokines and significantly enhanced numbers of CD4 and CD8 T cells as well as NK and NKT cells." (PMID 37711623, 2023). "Moreover, both CD4+ and CD8+ within the tumor displayed lower expression of PD-1, a marker of exhausted T-cells." (PMID 37586771, 2023). "The anti-tumor role of cDC1s is mostly due to their higher capacity for cross-presentation—leading to the activation of cytotoxic CD8 T-cells—and their aptitude to induce Th1 polarization of CD4 T-cells after antigen presentation." (PMID 37190135, 2023). "Moreover, the association between RAI2 expression and the abundance of six tumor-infiltrating immune cells was investigated by TIMER, including B cells, CD8+ T cells, CD4+ T cells, B cells, dendritic cells, neutrophils, and macrophages." (PMID 37064084, 2023). "Nevertheless, we failed to observe the activation of tumor-specific CD4+ T cells which mainly function in coordinating the immune response and require strong and sustained activation to produce IFNγ." (PMID 37296221, 2023). "The interaction of cancer cell-derived Gal-9 with Tim-3 on Th1 and Th17 cell surface has been identified to favor pro-tumour Th2 responses, as CD4+ T cells of this subtype do not express Tim-3." (PMID 36817445, 2023). "The level of CD19 protein and CD4/CD8 were increased in SFI group, indicating that SFI could enhance the immune function of tumor-bearing mice." (PMID 37355637, 2023). "The number of tumor-infiltrating T cells was significantly increased in GL261 tumors in pre-vaccinated mice as compared to the number occurring in GL261 tumors in non-vaccinated mice (unpaired Student’s t-test, CD3+: p < 0.0001; CD4+: p < 0.001)." (PMID 36993983, 2023). "Mice receiving 3 × 106 activated CLTCH129>Q-specific CD4+ T cells along with anti-CD40L were no longer protected from tumor challenge." (PMID 37400675, 2023). "Additionally, the percentage of activated CD4+and CD8+ T cells within tumour-infiltrating leucocytes (TILs) from Havcr1BKO mice were higher than those of control mice." (PMID 37857611, 2023). "In each of these tumor models, CD4 depletion at tumor implantation did not affect CD103+ CD8 T cell formation (Fig. 4bi–iv)." (PMID 37072485, 2023). "CCL2, CCR2, CD163, and CD4 were all widely expressed in both CNB and resected tumor samples." (PMID 37208442, 2023). "Besides, MiBaMc + PTDT + aPDL1 group showed the highest population of CD4+ helper T cells and CD8+ cytotoxic T cells within the tumor sections, as verified by the immunofluorescence staining." (PMID 37221237, 2023). "Multiplex immunohistochemistry staining of TILs (CD4, CD8, Foxp3, and PD-1) and immunohistochemical staining of CK and PD-L1 in the tumor and stroma was performed in tumor specimens of 107 NSCLC patients and correlated with clinical outcomes, as a single-center retrospective study." (PMID 36662367, 2023). "Here, we show that an inulin-enriched diet, a prebiotic known to promote immunostimulatory bacteria, triggers an enhanced Th1-polarized CD4+ and CD8+ αβ T cell-mediated anti-tumor response and attenuates tumor growth in three preclinical tumor-bearing mouse models." (PMID 36875124, 2023). "These CD8 + T-lymphocytes were interspersed among the tumor cells and were not accompanied by a significant population of CD4 + T-lymphocytes." (PMID 38079020, 2023). "Moreover, many genes related to an accumulation of T cells (Cd8a, Cd3e, Cd4), inflammations (Cxcl9, Tnf, Ifng), and a subset of M1-macrophage (Ciita, Nos2, Cd86) have elevated in anti-PD-1 antibody-treated IL-34KO CT26 tumor." (PMID 36798830, 2023). "Generation of CAR T cells led to increased expression of GFP relative to naïve T cells and coculture of anti-Her2 CAR T cells with AT-3-, E0771-, or MC38-Her2 expressing tumor cells led to a further and significant induction of GFP in both CD8+ and CD4+ CAR T cells." (PMID 37914685, 2023).
tumor (continued). "Moreover, positive correlations were detected between CD1C expression and infiltration levels of CD4+ T and CD8+ T cells, indicating a key role of CD1C in regulating tumor immunology." (PMID 36755259, 2023). "Studies revealed CD39 could serve as a marker for identification of tumor-specific T cells and CD39+CD8+, CD39+CD4+TILs were found to be beneficial for antitumor activity." (PMID 37520536, 2023). "BRD4 inhibitor expanded CD4+ and CD8+ T cell populations in the tumor microenvironment." (PMID 37685868, 2023). "Consistent with the data from our recognition assays, E6-specific CD4+ TILs were unable to limit the growth of HNSCC-56 tumor cells, which do not express MHC-II." (PMID 36512410, 2023). "In most cases, T-cells (both CD4+ and CD8+) in the tumor microenvironment display an activated phenotype represented by an increased expression of activation markers (i.e., CD69, CD25, CD95, CD44, and HLA-DR) and concomitant decrease in naive T-cells markers (CD45RA and CCR7)." (PMID 37835465, 2023). "Py8119 cells with Axl knockdown (by the CRISPR technology) transplanted into naive C57Bl/6 mice showed sensitivity to immunotherapy, delayed tumor growth, increased expression of MHC-I molecules and enhanced infiltration of mature DCs, CD4+ T cells, and CD8+ T cells in the tumor tissue." (PMID 37265798, 2023). "Studies have found that YAP1 inhibitors reduce the expression of PD-L1 in tumor tissues, promote the infiltration of CD8 T cells and CD4 T cells into tumor tissue, which disrupt the immunosuppressive microenvironment of cancer and improve the efficacy of HCC treatment." (PMID 38155974, 2023). "Both vaccines with short (Qβ-NeoAgS) and long (Qβ-NeoAgL) peptides significantly hindered tumor growth compared with the control, but Qβ-NeoAgL showed an improved antitumor efficacy accompanied by increased CD8 and CD4 T cells and lower MDSC tumor infiltration." (PMID 37629147, 2023). "In this study, the frequency of T-lymphocytes and their subsets in the schistosomal BCa group showed reduction in the level of total lymphocytes (CD3+), T helper (CD4+) cells, and cytotoxic T (CD8+) cells in tumor tissues compared to controls (group B) that was statistically significant (p < 0.001)." (PMID 37068081, 2023). "CD4+ T cells that recognize antigenic peptides presented on HLA class II are essential for inducing an optimal anti-tumor immune response, and adoptive transfer of tumor antigen-specific TCR-transduced CD4+ T cells with high responsiveness against tumor is a promising strategy for cancer treatment." (PMID 36939853, 2023). "Particularly, our previous study has reported that NYT may contribute to the reduction of CD4+ Treg cells in the spleens and tumor-draining lymph nodes derived from CT26-bearing WT BALB/c mice inoculated with irradiated tumor vaccine prophylactically." (PMID 37152373, 2023). "Moreover, the study also indicated that decreased KLRB1 expression correlated with tumor purity, immune score, and immune cell infiltration (B cells, CD8+ T cells, CD4+ T cells, neutrophils, dendritic cells, among others), cell markers, and immunotherapy." (PMID 37988189, 2023). "By isolating tumor-infiltrated EGFP+ leukocytes, we found that in tumors mixed with M-KO macrophages, CD11b+ Gr-1+ MDSCs (approximately 50%) were enriched, especially Ly6G+ G-MDSCs, while the infiltration of CD4+ and CD8+ T cells was lower." (PMID 37308559, 2023). "Moreover, metformin combined with platinum-based chemotherapy drugs significantly decreases CD4+ FOXP3+ Treg and CD4+/FOXP3− T helper cells in the tumor stroma of patients with advanced-stage EOC." (PMID 37686159, 2023). "Tregs can be CD4+ and CD8+T cells and are able to inhibit the proliferation and activation of effector T cells and to inhibit the secretion of T helper cell (Th) cytokines to inhibit the body’s anti-tumor immune response." (PMID 37138865, 2023).
tumor (continued). "IFN-γ and TNF-α are cytokines produced by activated TAA-specific CD4+ T cells that can both inhibit tumour survival and increase the expression of MHC class I molecules by the tumour cells, thereby enabling recognition by TAA-specific CD8+ cytotoxic T lymphocytes (CTLs)." (PMID 36851335, 2023). "Studies on patient tumor samples observed differences in the tumor microenvironment of HPV-positive and HPV-negative tumors, namely, greater T lymphocyte infiltration with a lower CD4/CD8 ratio in HPV-positive OSCC tumors, which correlated with better overall survival." (PMID 37296466, 2023). "The higher the infiltration density of CD4 + CD8 in TLS (p=0.01, cutoff= 1074.943733 cells/200xHPF), the longer the survival time of patients, suggesting that the total density of T cells plays a key role in tumor TLS." (PMID 36891293, 2023). "Moreover, overexpression of DSE significantly promoted the invasion of CD4+ and CD8 + T cells into the tumor." (PMID 37833287, 2023). "Case LYWS-1096 was a good example of the FL-like pattern; it comprised many tumor cells, positive for CD4 and strongly positive for TFH markers and negative for CD7." (PMID 37500795, 2023). "Moreover, protein expression of the β3-AR on murine lymphocytes of NB-bearing mice were confirmed by western blot analysis of lymphocytes obtained from TDLNs and immunofluorescence of CD4+ and CD8+ T cells stained for β3-AR on tumor mass sections." (PMID 36854895, 2023). "cDC2 presented tumor-derived antigens to CD4+ Tconv, but failed to support antitumor CD4+ Tconv differentiation." (PMID 36982677, 2023). "have designed a nanoparticle (NPsiCTLA-4) that could distribute the CTLA-4-siRNA to the CD4+ and CD8+ T cell subsets present in the tumor microenvironment." (PMID 37600822, 2023). "Moreover, human leukocyte antigen (HLA) molecules of both glioblastoma tissues and tumor cell lines present bacteria-specific peptides, which are recognized by tumor-infiltrating lymphocyte (TIL) CD4+ T-cell clones." (PMID 37828613, 2023). "VV combined with ICIs reduced the number of PD-L1+ cells and promoted the non-redundant tumor infiltration of effector CD8+CD4+ T cells while increasing the expression of IFN-γ, ICOS, granzyme B, and perforin." (PMID 36604694, 2023). "Taken together, these results confirmed that a few CD4+ effector T cells can indirectly eradicate established IFN-unresponsive, MHC-deficient tumours that evade CD8+ T cell immunity independent of NK cells." (PMID 37316667, 2023). "Investigators have detected that the higher frequencies of IFNγ-producing CD4+ T cells and higher amount of secreted IFNγ before the induction treatment are characteristic of patients who do not show tumour recurrence at 6 months." (PMID 36928373, 2023). "The vaccine showed CD4+ and CD8+ T cell response post vaccination with cytotoxic phenotype which could move to the tumor and mediate the killing of tumor cells." (PMID 36845151, 2023). "Tumor volume, the frequency and phenotypes of WT1-specific CTLs in CD8+ T cells in peripheral blood (PB) and tumor-infiltrating lymphocytes (TILs), as well as the proportion of interferon-gamma (INF-γ)-producing CD3+CD4+ T cells pulsed with WT135–52 peptide in splenocytes and TILs were determined." (PMID 36803483, 2023). "CDK4/6 inhibition suppresses CD4+ Tregs more than CD8+ cytotoxic T cells, increases the CD8+ T cells/Tregs ratio in the tumor microenvironment, and, when combined with an ICI, leads to the clearance of tumor cells by cytotoxic T cells." (PMID 37298520, 2023). "Moreover, we performed flow cytometry analysis to evaluate TIGIT expression ex vivo in tumor, spleen, or lymph node as single cell suspensions, focusing on the CD45+, CD3+, CD4+, CD8+ and Treg populations." (PMID 37799715, 2023).